BRCA1 (BRCA1 DNA repair associated)
Diseases named in the same sentence as BRCA1 in open-access papers (continued):
Sharing a sentence is not in itself a finding about the gene and the disease.
cancer (continued). "Pathogenic variants in the BRCA1 and BRCA2 genes appear in different types of cancer, among which they are more frequently found in breast, ovarian, pancreatic, or prostate cancer." (PMID 37296748, 2023). "Genetic factors represent one of the major driving causes of OC onset, where the tumor-suppressor BRCA1 and BRCA2 gene alterations are the most associated with the increased cancer susceptibility." (PMID 38069422, 2023). "For example, PARP inhibitors such as olaparib (Lynparza®) have shown remarkable therapeutic efficacy against BRCA1/2-mutant cancers through synthetic lethality." (PMID 37174127, 2023). "PARP inhibition was first described in cancer cells with defective BRCA1/BRCA2 protein function, and then clinical trials confirmed the effectiveness of PARP inhibitors as monotherapy in patients with BRCA1(−/−) and BRCA2(−/−) tumors." (PMID 36769087, 2023). "Out of 940 BRCA1/2 females (assigned at birth), 431 had a prior history of some cancer at the time of genetic diagnosis, and 13 BRCA1/2 carriers had incomplete medical records or had lost follow-up." (PMID 36831416, 2023). "In our study, we found a parallel tendency of a TMB increase between SETD2 deleterious mutations and DDR gene mutations including BRCA1/2, MMR genes, and POLE/D1 across seven cancer types." (PMID 37479966, 2023). "The contributions of BRCA1 to the metabolic features of cancer cells were investigated by Privat and co-workers." (PMID 37109525, 2023). "Nonetheless, there are preclinical and clinical evidence for the activity of olaparib monotherapy in BRCA1/2 wild-type cancers." (PMID 37582853, 2023). "These tumours often show strong geno-phenotypic correlation, with BRCA1 carriers showing increased representation of basal phenotype cancers in women, and BRCA2 carriers showing increased representation of micropapillary-type cancers in men." (PMID 36831687, 2023). "Data on heterozygote PALB2 disease-causing variant carriers compared to BRCA1/BRCA2 carriers are still scarce in terms of both cancer incidence, spectrum of cancers and clinical outcomes." (PMID 37686625, 2023). "Many authors argue that the identification of a BRCA1/2 PV in a person after cancer diagnosis is a failure of prevention." (PMID 37887578, 2023). "DHX9 interacts with cancer-associated genes such as CBP, BRCA1 and EGFR to regulate their transcription and translation." (PMID 37305700, 2023). "BRCA is a cancer suppressor gene, including BRCA1 and BRCA2, identified in 1990 and 1994, respectively." (PMID 37476378, 2023). "Their headline rate of 56% for BRCA1 is extremely high, but caution is necessary in translating this to all metaplastic cancers as there is likely a strong testing bias." (PMID 37592173, 2023). "The content was updated to emphasize the association of BRCA1/BRCA2 variants with prostate, pancreatic, and possibly other types of cancer." (PMID 37760455, 2023). "Horvitz-Thompson estimates for the prevalence of BRCA1/2 carriers in various countries depending on cancer type." (PMID 36753473, 2023). "Both BRCA1 and BRCA2 are needed for HR and consequently cancer cell lines deficient in BRCA1 or BRCA2 are highly sensitive to PARP inhibitors." (PMID 37773077, 2023). "For example, the amplification of the HER2 gene can lead to the rapid growth and spread of cancer cells, and the expression of BRCA1, BRCA2, EGFR, and PIK3CA can also increase the proliferation and migration risk of cancer cells." (PMID 37960513, 2023). "Genome hypermethylation in BRCA1 carriers has been shown to be significantly correlated with cancer development." (PMID 37108398, 2023). "Overall, animal models have proven indispensable in elevating our understanding of BRCA1 and its pivotal involvement in the inception and evolution of cancer." (PMID 37762577, 2023). "Especially, when there are defects in DNA repair caused by mutations of BRCA1/2, the inhibition of PARP1 results in unrepairable DNA and the apoptosis of cancer cells." (PMID 37215456, 2023).
cancer (continued). "In line with this idea, CRISPR KO data from the CCLE database revealed a similar CERES project score for FBXO9 as that of BRCA1/2, suggesting that OV cancer cells exhibit comparable dependency on FBXO9 as on BRCA1/2." (PMID 38136595, 2023). "Other high-penetrant cancer genes BRCA1, APC, STK11 and moderate-penetrant genes BRIP1, CDKN2A, FANCI and MET had a similar frequency 1 (5.8%)." (PMID 37277882, 2023). "The present study assessed the modulation of miR-155-5p expression in peripheral white blood cells (WBCs) of BC and OC patients and cancer-free BRCA1-methylation female carriers." (PMID 37240365, 2023). "The proportion of germline SV mutations in BRCA1 and BRCA2 was markedly elevated in OC (BRCA1, 3.4%; BRCA2, 1.7%) and PC (BRCA2, 2.2%) compared to other cancers, as was the proportion of germline SV mutations in the HR genes RAD51C and RAD51D in OC." (PMID 37821580, 2023). "Cancer centres located in other geographical regions where germline BRCA1 Exon 13 duplication occurs frequently should be aware of the possible under reporting of this large rearrangement by the myChoice® CDx." (PMID 38201604, 2023). "It has been demonstrated that BRCA1-mutant cancer cells have impaired DNA DSB repair and are particularly vulnerable to ionizing radiation, while the expression of BRCA1 restores the radioresistance." (PMID 37958947, 2023). "This is the first study to determine the cancer risks in relatives of BRCA1/2 carriers in the Chinese population." (PMID 36861435, 2023). "Compared to the full-length BRCA1 spliceosome, BRCA1--Δ11q clearly promotes cancer cell growth as well as resistance to PARP inhibitors and cisplatin." (PMID 37144133, 2023). "Researchers have devoted considerable effort to identifying and characterizing RAD52 inhibitors for synthetic lethality strategies in BRCA1/2-depleted cancers and in cells with drug-induced BRCA1/2 depletion." (PMID 36980703, 2023). "A meta-analysis suggests that PGVs in BRCA1, BRCA2, and MMR genes contribute to reduced penetrance to cancer risk in children and adolescents." (PMID 37916805, 2023). "Mutated BRCA gene distribution was statistically significantly different (p = 0.015): most cancer patients were BRCA1 PV carriers (73.6%) whereas in the cancer-free cohort an almost even representation was seen for both genes." (PMID 37370730, 2023). "Their confocal and immunoelectron microscopy studies showed that BRCA1 is present in the mitochondria of several human cancer cell lines and in primary breast epithelial cells." (PMID 37109525, 2023). "Pharmacological inhibition of PARP is synthetically lethal, especially in cancer types with genetic or functional defects in BRCA1/2 genes or other genes in the homologous recombination pathway." (PMID 36978917, 2023). "Three of the 96 Israeli Arab patients with cancer were heterozygotes (4%); two of them carried the MHPV c.5074+3A>G in BRCA1, previously reported as a common variant in the Arab population." (PMID 38201524, 2023). "Loss-of-function (LOF) germline mutations in HRR genes, such as BRCA1 and BRCA2, significantly contribute to the elevated risk of cancer in heterozygous carriers." (PMID 37298484, 2023). "ShallowHRDv2 is a software tool trained on pan-cancer series of ~1000 sWGS partially annotated with BRCA1/2 status that takes as an input normalized copy number alteration (CNA) profile from sWGS (or WGS) and provides HRD status based on LGA-score." (PMID 37945748, 2023). "BRCA1-mutant cancers have markedly increased oxidative stress, which would require robust BER pathways to repair damaged DNA and maintain cell viability." (PMID 36683914, 2023).
cancer (continued). "Recent reports based on a substantial number of cases, warrant need for population-based research to determine implications of constitutional methylation of tumor suppressor genes such as BRCA1 occurring in healthy tissue in the prediction of cancer." (PMID 37752189, 2023). "Here we conducted a Phase II study to evaluate the safety and efficacy of olaparib and durvalumab (O + D) in patients with advanced solid and predominantly rare cancers, harbouring either somatic or germline BRCA1/2, or other HRR gene alterations." (PMID 37365284, 2023). "Linking mutations in the BRCA1 and BRCA2 genes to the general mechanisms of genome stability and DNA repair is critical to ensure the rationalized choice of anti-cancer therapy." (PMID 36902416, 2023). "In clinical practice, genetic testing for BC risks has been based chiefly on BRCA1/2 gene analysis, despite new evidence suggesting the clinical significance of a broader number of cancer-related genes." (PMID 37791908, 2023). "Accordingly, a recent study found that BRCA1/2-defective cancer cells rely much more on TLS for repair of PRIMPOL-dependent ssDNA gaps." (PMID 36749784, 2023). "The inhibition of the other intact DNA repair pathways is a potential strategy to expand the use of PARP inhibitors to treat cancers that are defective in DNA repair genes beyond BRCA1/2." (PMID 36794257, 2023). "Several genome-wide screens have identified APE2 as a synthetic lethal target for deficiencies of BRCA1, BRCA2 or TDP1 in cancer cells." (PMID 36755963, 2023). "Mutations in Tg46 tumors impinged on cancer driver genes mostly related to phosphoinositide 3-kinases (PI3K)-Akt signaling (e.g., c-Met) and DNA repair (e.g., Brca1) pathways." (PMID 36693903, 2023). "53BP1 has recently attracted particular attention because of its role in the pathway choice between NHEJ and HR and its relevance to PARPi treatment of BRCA1-mutant cancers." (PMID 36794849, 2023). "Thus, PARP inhibitors could cause 'synthetic death' in BRCA1/2-deficient cancers." (PMID 37641116, 2023). "The concept of synthetic lethality promotes the development of PARP inhibitors in cancers possessing the defect of homologous recombination repair (HRR), especially those with biallelic loss of BRCA1 and BRCA2." (PMID 36765522, 2023). "Among these genes we identified was BRCC3, a component of the BRCA1 complex that guards genome integrity and exerts tumor suppressive activity during cancer development." (PMID 37887275, 2023). "Identifying BRCA1 or BRCA2 PV has important clinical implications in risk management and cancer treatment decisions." (PMID 38067403, 2023). "Inhibiting RAD52 induces synthetic lethality in many cancer cells with defective DNA repair-related proteins, such as BRCA1, BRCA2, PALB2, XAB3, and RAD51 paralogues (i.e., RAD51B, RAD51C, RAD51D, XRCC2, XRCC3)." (PMID 36980703, 2023). "In fact, polyadenosine diphosphatase ribose polymerase (PARP) inhibitors, such as olaparib (Lynparza®), have shown remarkable therapeutic efficacy against BRCA1/2-mutant cancers through synthetic lethality." (PMID 37174127, 2023). "BRCA1 knockdown represses cancer cell growth, and high BRCA1 expression predicted poor relapse-free survival in BC patients." (PMID 37109525, 2023). "The model allows for personalising PCa risks on the basis of a consultand's age, detailed cancer FH, moderate- to high-risk BRCA2, HOXB13, and BRCA1 PVs, and a 268-SNP PGS." (PMID 36493335, 2023). "Cancers with HRR defects (e.g., BRCA1 and BRCA2 mutations) are targets for PARP inhibitors (PARPis) based on the exploitation of “synthetic lethality”." (PMID 37892162, 2023).
cancer (continued). "Animal models have been instrumental in enriching our comprehension of the intricate functions of BRCA1 within the landscape of cancer initiation and progression." (PMID 37762577, 2023). "FANCD2 overexpression, which has been reported in different types of cancers, was found to confer resistance to PARPi by stabilizing replication forks in BRCA1/2-mutant cells." (PMID 37609662, 2023). "For example, deletion of Polθ is synthetic lethal with various DNA repair genes, including BRCA1/2 mutations and can synergise with PARP inhibitors in HR-defective cancers." (PMID 36980782, 2023). "Correspondingly, the deubiquitinating enzyme USP9X stabilizes BRCA1 from degradation and promotes resistance to DNA-damaging agents in various types of cancer cells." (PMID 36694209, 2023). "At the same time, in a large-scale study of BC women aged 35–59 years, who were mainly of Northern and Western European descent, PVs in CHEK2, ATM, PALB2, and PMS2 genes were the most frequent among the 25 cancer genes tested, after PVs in BRCA1/2." (PMID 37791908, 2023). "All men carrying BRCA1 or BRCA2 mutations should start cancer screening at the age of 40 with yearly PSA and consider the same in men with BRCA1, ATM, HOXB13, and DNA MMR mutations." (PMID 37021836, 2023). "Of these, the most commonly seen are in the Breast Cancer gene 1 (BRCA1), Breast Cancer gene 2 (BRCA2), Checkpoint kinase 2 (CHEK2) and partner and localizer of the BRCA2 gene (PALB2) tumour suppressor genes." (PMID 36831687, 2023). "However, the recent introduction of poly ADP ribose polymerase (PARP) inhibitors to treat patients with BRCA1/2 variants resulted in more expansion of the testing guidelines to include all patients who may potentially benefit from certain anti-cancer therapy used in the setting of BRCA1/2 variants." (PMID 37781190, 2023). "On the other hand, the cancer risks associated with PVs in PALB2 are becoming more and more similar to those for BRCA1 and BRCA21,31." (PMID 37237042, 2023). "For example, in experiments using cultured cancer cells, when Aspm expression was suppressed, BRCA1 expression was also decreased and the reverse has also been confirmed." (PMID 38019816, 2023). "In general, the application of comparative genomics to cancer genetics has proved fruitful, notably in studies that examine selective pressure across all mammals on cancer-related genes such as BRCA1/2." (PMID 37759191, 2023). "Some studies have reported the transcriptional and post-transcriptional regulation of hnRNPA2B1 in cancer, that c-Myc and BRCA1 promoted hnRNPA2B1 transcription, while activation of Fyn and Nm23-H1 stabilized hnRNPA2B1 protein expression." (PMID 37716979, 2023). "In the present study, we applied NGS, Sanger sequencing, and MLPA to screen germline SNV/indel and CNVs in BRCA1/2 among 100 BC patients enrolled at the only tertiary cancer‐specialized public hospital located in business capital, Dar es Salaam, Tanzania." (PMID 35908255, 2023). "Collectively, these studies illuminate the molecular mechanisms through which BRCA1 impacts DNA repair and cancer development." (PMID 37762577, 2023). "The development of GC is associated with mutations in oncogenes, cancer suppressor genes, and DDR-related genes, such as KRAS and BRCA1/2, which promote genomic instability and carcinogenesis." (PMID 37457685, 2023). "The Slovenian population was statistically significantly (p < 0.05) enriched for pathogenic variants in ATM, BRCA1, and CDH1 genes when compared to the gnomAD non-cancer control population." (PMID 37002323, 2023). "BRCA1 and BRCA2 mutations responsible for the majority of homologous recombination deficient (HRD) cancers are prevalent in solid tumors of the breast, ovaries and prostate." (PMID 36792656, 2023). "CNV analysis indicated that heterozygous deletion of ARID1A was prevalent in ESCA and KICH; BRCA2 CNV deletion was more common in Pan-cancer than BRCA1 CNV deletion." (PMID 37264024, 2023).
cancer (continued). "In cancer cell lines with defective breast cancer genes 1 and 2 (BRCA1/2), the PARP’s roles emerged as even more essential for the survival." (PMID 37570820, 2023). "FA displays an autosomal recessive inheritance, but cancer risk is associated with some heterozygous mutations in the following genes: BRCA2 (FANCD1), BRIP1 (FANCJ), PALB2 (FANCN), RAD51C (FANCO), BRCA1 (FANCS)." (PMID 37239385, 2023). "Overall, there seems to be sufficient research evidence to consider the potential implications of the BRCA1 constitutional methylation testing in normal tissue as well as other tumor suppressor genes for the prediction of cancer." (PMID 37752189, 2023). "Since BRCA1 and BRCA2 are involved in DNA repair, mutations in these genes can cause genetic errors leading to cancer." (PMID 37445860, 2023). "Its knockdown has been proposed to induce ‘BRCAness’ by downregulation of BRCA1 and the Fanconi anemia pathway, thereby sensitizing cancer cells to olaparib." (PMID 37609662, 2023). "The analysis of the BRCA1/2 and/or other HR genes’ mutational statuses offers a direct way to investigate the cause of HRD in cancer cells." (PMID 37761329, 2023). "BAP1 is a multifunction suppressor of cancer that influences the immune system, cell cycle control, DNA damage response via its connection with BRCA1, chromatin remodeling, and DNA damage response." (PMID 37770494, 2023). "With regard to predictive makers, several miRNAs, including miR-146a, miR-146b-5p and miR-182, have been reported to reduce BRCA1 protein expression, with miR-182 expression also showing sensitivity to PARPi in cancer cell lines." (PMID 36831687, 2023). "Further studies and advancements in this field are needed to fully explore the potential of epigenetic editing as a therapeutic strategy for BRCA1-related cancers." (PMID 37761820, 2023). "This is likely due to health authority policy at the time, which permitted publicly funded BRCA1/2 testing only for individuals with a cancer diagnosis or known familial PV." (PMID 37887578, 2023). "PARPi offer an advantageous treatment option for patients with BRCA1/2 mutant tumors by exploiting synthetic lethality, but as with many cancer treatments, resistance eventually occurs." (PMID 37429899, 2023). "Previous studies have examined the correlation between BRCA1/2 mutation and PARG inhibitor sensitivity in numerous cancer cells." (PMID 36053937, 2023). "Given the high incidence of BC and the relatively low frequency of PVs in BRCA1 or BRCA2 in these carcinomas, there is a clear demand for a sensitive method to enrich for HRD tumors in a fast and cost-effective manner." (PMID 37725154, 2023). "Overall, 67% of participants were willing to undergo BRCA1/2 testing, with proportions of the general public (58%), cancer patients (70%), clinicians (88%), and researchers (90%)." (PMID 35629239, 2022). "Cancer worry was related to time since BRCA1/2-PV diagnosis and being before or within the guideline age for RRSO (BRCA1: 35–40 years and BRCA2: 40–45 years)." (PMID 34997316, 2022). "Adult daughters of unaffected BRCA1/2 (a type of HBOC) carriers showed clinical levels of cancer-related distress and worries both regarding their mothers and other relatives." (PMID 35162625, 2022). "It is, therefore, important to separately consider when assessing cancer risks for BRCA1/2 carriers with different genotypes." (PMID 35378767, 2022). "As expected, the protein level of DKK1 in the culture medium of dobutamine-treated BRCA1 knock-down cancer cells was elevated." (PMID 35517499, 2022).